SKP2 (S-phase kinase associated protein 2)
Diseases named in the same sentence as SKP2 in open-access papers (continued):
Sharing a sentence is not in itself a finding about the gene and the disease.
tumor (continued). "In univariate analyses, high tumor expression of Skp2 correlated (p = 0.050) with reduced disease-specific survival (DSS)." (PMID 23497154, 2013). "It has previously been shown that Skp2 is highly expressed in NPC tumor with poor prognosis, and the stability of Skp2 is regulated by AKT." (PMID 24156782, 2013). "We have recently shown that mechanistically Wnt10b-driven (Wnt10bTG) tumours degrade the tumour suppressor p27Kip1 in a SKP2-independent manner mediated by CUL4A E3-ligase activity leading to increased proliferation." (PMID 23307470, 2013). "In accordance with the link between Sin3A function and c-Myc expression, we detected increased levels of c-Myc protein and the c-Myc target Skp2 in K5-SOS Hdac1Δ/Δep tumours." (PMID 24240174, 2013). "Skp2 expression correlated closely with the T category (p = 0.035) and the pathological tumor-node-metastasis (TNM) stage (p = 0.027)." (PMID 22533738, 2012). "To date, no specific inhibitor of SKP2 has been identified however three SMIs have been shown to downregulate SKP2 activity, and exhibit anti-tumor effects in preclinical studies." (PMID 23226679, 2012). "In the present study, Skp2 staining of ESCC tissue revealed immunoreactivity primarily in nuclei within tumor cells." (PMID 22533738, 2012). "In support of this notion, Skp2 cytoplasmic localization has been observed in many clinical tumor samples and is correlated with aggressive malignancy and poor diagnosis." (PMID 23230084, 2012). "Cytoplasmic Skp2 expression, cytoplasmic p27 expression, tumor size, histological grade, and lymph node status were also significantly associated with OS." (PMID 23300741, 2012). "Altogether, our results suggest that in our experimental settings, SIRT3 inhibited tumor growth mainly through deacetylation of Skp2 oncoprotein." (PMID 23230084, 2012). "Overall, elevated SKP2 expression has been shown to correlate with a poor prognostic outcome, tumor size, dedifferentiation, advanced grade, and metastasis." (PMID 23226679, 2012). "In univariate analyses, high tumor expression of Ki67 (P = 0.007) and Skp2 (P = 0.050) correlated with shorter disease-specific survival (DSS)." (PMID 23071715, 2012). "Age, sex, tumor thickness, ulceration and location and cytoplasmic Skp2 expression were included in the regression model." (PMID 21386910, 2011). "Conversely, RNA interference (RNAi)-mediated knockdown of SKP2 expression inhibits tumour growth in a mouse transplant model." (PMID 21182779, 2010). "Skp2 is frequently overexpressed in tumor cell lines, and forced expression of Skp2 in quiescent fibroblasts induces DNA synthesis." (PMID 20508867, 2010). "Skp2 cytoplasmic localization has been observed in many clinical tumor samples and is correlated with aggressive malignancy and poor diagnosis." (PMID 19549334, 2009). "In this study, Skp2 expression was found to be significantly correlated with advanced T stage, larger tumor size and necrosis, while Cks1 only correlated with tumor size." (PMID 18922157, 2008). "Skp2 expression was significantly correlated with tumor stage (P < 0.001) and tumor size (P < 0.001), as well as tumor necrosis (P = 0.001)." (PMID 18922157, 2008). "A significant inverse correlation was found between Skp2 expression and tumor differentiation (P = 0.001), ER expression (P = 0.006), and PgR expression (P = 0.005)." (PMID 18644126, 2008). "Low p27Kip1 expression and Skp2 expression were correlated with larger tumor size and higher stage, as well as tumor necrosis." (PMID 18922157, 2008). "Skp2 expression before preoperative chemotherapy was inversely related to p27Kip1 levels, tumor grade, and expression of estrogen and progesterone receptors." (PMID 18644126, 2008).
tumor (continued). "It will also be necessary to use model organisms to investigate how much E2F regulation contributes to pRB's role as a tumor suppressor compared with Cdh1/Skp2 or others." (PMID 17854503, 2007). "Our findings provide a PDCD11‐targeted therapeutic rationale for specially degrading the C‐MYC oncoprotein by efficiently harnessing the SCFSKP2‐possessed E3 ubiquitination activity, which results in a reduced SKP2 expression to avoid triggering SKP2‐promoted tumor progression." (PMID 40051297, 2025). "In addition, Wei Wenyi’s team found that the K68/K71 acetylation modification of SKP2 can promote its cytoplasmic localization and enhance tumor metastasis by degrading E-cadherin, while SIRT3 deacetylase can reverse this process." (PMID 40534867, 2025). "Moreover, the differential expression of TRIM69, Ube2j1, ZBTB4, and SKP2 likely serves a critical function in modulating tumor immune infiltration." (PMID 40697329, 2025). "Thus, PDCD11 upregulates C‐MYC protein but not C‐MYC mRNA to activate downstream effector molecules including but not limited to E2F1, CCNE2, and SKP2, thereby exerting its tumor‐promoting functions." (PMID 40051297, 2025). "ADAR2 editing modulates CDC14B/Skp2/p21/p27 axis, suppressing tumor progression." (PMID 40852728, 2025). "Additionally, Skp2 was identified as a major target of the tumor suppressor miRNA miR-7, with its downregulation resulting in increased p27 levels and subsequent cell growth arrest." (PMID 40534867, 2025). "The function of SKP2 is regulated by a variety of post-translational modifications, among which O-GlcNAc modifications and ubiquitination modifications play an important role in tumor immune escape." (PMID 40534867, 2025). "These organoids serve as valuable preclinical models for assessing the anti-tumor efficacy of SKP2 inhibitors, and for validating the expression patterns of PDGFD and PDGFRB, as well as the spatial distribution and binding characteristics of ligand-receptor interactions." (PMID 40271075, 2025). "The inhibition of SHIP2 by HBV X increased chemoresistance and tumor metastasis via Skp2 in HCC." (PMID 39199296, 2024). "At present, the role of SKP2 in tumor-initiating properties in OS is still unexplored." (PMID 38355807, 2024). "Furthermore, SKP2 inhibitors have been found to restrict stem-like properties and potentiate the sensitivity to chemotherapy in other tumor models." (PMID 38355807, 2024). "Together, these functional studies with nondegradable Skp2AA demonstrate that knockdown of RCC1 could suppress the growth of STS tumor in vivo by downregulating the Skp2 abundance to block the cell proliferation." (PMID 38561375, 2024). "Depletion of SKP2 reduces tumor growth in xenograft mice models." (PMID 38559562, 2024). "Furthermore, we found that small-molecule inhibitors of SKP2 exhibited anti-tumor activities in vivo and in OS organoids as well as synergistic effects when combined with a standard chemotherapeutic agent." (PMID 38355807, 2024). "Skp2 has been reported to promote cell proliferation and tumor progression in HCC." (PMID 39199296, 2024). "For example, SKP2 is overexpressed in breast, prostate, colorectal, and pancreatic cancers as well as lymphoma, melanoma, and nasopharyngeal carcinoma, and is highly correlated with poor tumor prognosis 22-24." (PMID 38903918, 2024). "In addition, MYOD1 directly regulates SKP2 (S-phase kinase associated protein-2) in RMS, a substrate recognition subunit of the E3 ubiquitin ligase complex that is necessary for tumor cells to maintain cell cycle progression." (PMID 39902277, 2024).
tumor (continued). "Therefore, it is unsurprising that low levels of various tumor suppressors, particularly p27KIP1, are inversely correlated with the elevated expression of SKP2 across multiple tumor types, including HCC." (PMID 39064589, 2024). "Next, we evaluated whether SKP2 promoted tumor growth by subcutaneously engrafting JR1 cells expressing shSKP2.1, shSKP2.2, or scrambled shRNA (shSCR) as control." (PMID 38102140, 2023). "In our study, distinct SKP2 expression was found in various normal organ and neoplasm cells." (PMID 37308972, 2023). "Collectively, this study provided a comprehensive analysis of SKP2 in human neoplasms." (PMID 37308972, 2023). "SKP2 plays an essential role in multiple neoplasms and may serve as a marker for treating and identifying these neoplasms." (PMID 37308972, 2023). "It is also required for the high-level expression of the SKP2 gene in many human tumor cell lines." (PMID 36770809, 2023). "Skp2 orchestrates with Myc to recruit p300 to the promoter of zinc finger E-box binding homeobox 1 (Zeb1), which leads to induction of Zeb1 transcription, finally promoting tumor migration and invasion." (PMID 37089937, 2023). "Exploring the relationship between SKP2 and these indicators may help identify the marker role of SKP2 in neoplasms." (PMID 37308972, 2023). "Further, the current study revealed a series of drugs that may be suitable for neoplasm patients with high SKP2 expression." (PMID 37308972, 2023). "Knockdown of Skp2 induces p27 expression and cell cycle arrest which may enhance the anti-tumor effect of cisplatin by DNA damage." (PMID 37532777, 2023). "Besides, it is important to consider the contributions of BIRC5 and SKP2 to the tumor microenvironment." (PMID 37679418, 2023). "Notably, the relationship between SKP2 expression and both immune cell infiltration levels and immune environment scores varied with tumor type, implying the complex mechanisms of SKP2 in neoplasms." (PMID 37308972, 2023). "Take curcumin, for example, the observed tumor inhibition effects of curcumin might attribute to several inhibitor mechanisms including inhibition of Skp2." (PMID 37089937, 2023). "In a first step, we investigated SKP2 levels across different tumor types finding that SKP2 was strikingly overexpressed in RMS compared to control healthy skeletal muscle tissue and exhibited the highest levels of expression among all the adult and pediatric tumors analyzed." (PMID 38102140, 2023). "Previous studies have revealed the molecular mechanism of the gene in a single neoplasm, but whether SKP2 had a similar molecular mechanism in a variety of tumors was unknown." (PMID 37308972, 2023). "Taken together, the overexpression of SKP2 was identified in most neoplasms." (PMID 37308972, 2023). "Further, SKP2 was confirmed as a target of YAP in promoting tumor cell proliferation." (PMID 35685435, 2022). "The signature reflects the level of SKP2 activity, stratifying BC patients into two groups with significantly different protein levels of SKP2 ubiquitination substrate p27 (t-test p < 0.01) and recapitulating the expression patterns of SKP2 between tumor and normal tissue (Spearman’s ρ = 0.39)." (PMID 35169199, 2022). "To prove this hypothesis, we stratified the patients of our cohort treated with cisplatin or carboplatin as first-line treatment according to the median level of SKP2 in the tumours." (PMID 35197103, 2022). "SKP2 is hypothesized to operate as an oncoprotein since it is responsible for the degradation of the tumor suppressor proteins." (PMID 35865469, 2022). "Skp2 participates in the regulation of cell growth cycle and promotes the growth of tumor cells." (PMID 35845132, 2022). "Thus, our data reveal that Aurora-A/FOXO3A/SKP2 axis promotes tumor progression in ccRCC, and the double inhibition of SKP2 and Aur-A shows significant synergistic effect, which indicates a potential new therapeutic strategy for ccRCC." (PMID 35831273, 2022).
tumor (continued). "Paradoxically, however, others have shown that reduced SKP2 expression leads to P27 accumulation and is associated with mitotic defects and polyploidy, suggesting SKP2 may also exhibit a tumor suppressive role." (PMID 36496990, 2022). "Previous literature has shown that Skp2 is closely related to the development of tumor cells." (PMID 35845132, 2022). "Therefore, MLN4924 inhibited the proliferation of tumor cells by blocking the ubiquitin ligase activity of Skp2 on the one hand, and downregulating SKP2 expression by inducing the phosphorylation and inactivation of YAP on the other hand." (PMID 35685435, 2022). "Thus, it appears that SKP2 harbors both oncogene-like and tumor-suppressor-like properties depending on the cellular context and the aberrant regulation of the substrate targets of the SCFSKP2 complex." (PMID 36496990, 2022). "YAP promoted tumor cell proliferation by up-regulating SKP2 expression in multiple cancers." (PMID 35685435, 2022). "Glycolysis in HER2-positive tumour cells is regulated by the SKP2-SCF E3 ubiquitin ligase." (PMID 36064706, 2022). "Skp2 mainly degrades the Cyclin-dependent kinase inhibitor (CKIs) which can inhibit the G1 to S phase transition of the cell cycle and subsequently regulates tumor proliferation and metastasis." (PMID 34702937, 2021). "The development of Skp2-Cks1 inhibitors might provide a novel and potential target for Skp2-overexpressed tumor patients." (PMID 34702937, 2021). "The downregulated SKP2 caused accumulation of its substrates, p27 and p21, which further inhibited the activity of the G1 phase-related protein, CDK2, leading to inhibition of cell proliferation and tumor formation." (PMID 33628597, 2021). "The Skp2 inhibitor SMIP004 is able to increase the curative effect of tumor radiotherapy." (PMID 35006464, 2021). "SIRT2/3 may induce Skp2 deacetylation and subsequent degradation to abolish the effects of Skp2 on p27 and increase the expression of tumor suppressor p27 to affect NSCLC cell growth." (PMID 34068643, 2021). "Furthermore, recent studies have shown that SKP2 plays an oncogenic role in promoting tumour cell growth and migration in HCC." (PMID 33422101, 2021). "Skp2 is identified as an oncoprotein that exhibits tumor-promoting functions in malignancies." (PMID 33621206, 2021). "Included factors were primary tumor (T) (I, II vs III, IV), N stage (N0 vs N1–3), tumor grade (well to mod vs poor), lymphatic invasion, vascular invasion, neural invasion, SKP2 expression, Beclin-1 expression, tumoral FOXP3 expression, and number of Tregs (<15/HPFs, ≥15/HPFs)." (PMID 34414959, 2021). "Therefore, SKP2 exerts its oncogenic function mainly through degradation of its tumor suppressive targets." (PMID 33130827, 2021). "Interestingly, acetylation of p300 by SKP2 changes the location of SKP2 from the nucleus to the cytoplasm, resulting in an increase in cell proliferation and tumour regeneration." (PMID 33906413, 2021). "The results proved that ov-SKP2 or in-miR26a could reverse these biological functions as a tumour suppressor by silencing lincSCRG1 in HCC cells, displaying the contrasting results of sh-lincSCRG1." (PMID 33422101, 2021). "Furthermore, safranal-treated tumor tissues exhibited a reduction in Skp2, E2F1, NF-κB p65, p-IκBα (Ser32), c-MYC, p-Rb (Ser807), CDK4, CDK6, and CDK2 and an elevation of p27 and p21 protein levels." (PMID 33392189, 2020). "One limitation of this study is the lack of in vivo experiment to define whether diosgenin retards tumor growth via reduction of the Skp2 level in mice." (PMID 32626765, 2020). "Interestingly, SKP2 molecules are sustained by TRβ2 that antagonizes the tumor-suppressive function of TRβ1 to promote development of RB1-deficient malignancies." (PMID 32824373, 2020). "Skp2 was significantly over expressed in various types of tumor tissues." (PMID 32165861, 2020). "Additionally, Skp2 inhibition maintains quiescence and suppresses tumor progression in multiple transgenic mouse models." (PMID 33392189, 2020).
tumor (continued). "Furthermore, despite the pharmacological limitations of C25 SKP2 inhibitor used in this study, significant reduction of tumor burden was observed with a short monotherapy regiment in an aggressive xenograft model of T-ALL." (PMID 31772299, 2020). "Several compounds that effectively suppress Skp2 expression have been tested in tumor cells." (PMID 32165861, 2020). "For instance, F‐box protein FBXW7 functions as a tumor suppressor by promoting proteasomal degradation of c‐Myc, Cyclin E, and Notch, whereas SKP2 functions as an oncogene by promoting degradation of tumor suppressors and activating AKT signaling by abrogating its proteasomal degradation." (PMID 30714168, 2019). "Skp2 is also highly expressed in tumor cells and promotes cell proliferation." (PMID 31791390, 2019). "Transcript expression of SKP2, a SCFSKP component, was elevated in RB1-defective TNBCs, suggesting that in these tumours, SKP2 activity might buffer the effects of RB1 dysfunction." (PMID 29915391, 2018). "In triaging the candidate Rb-synthetic lethal effects that operated in TNBC tumour cells to identify those with greatest penetrance, we identified a series of pharmacologically tractable effects, one of which, SKP2, we validated using both genetic and pharmacological methods." (PMID 29915391, 2018). "Chemical-induced skin tumorigenesis is inhibited in SKP2(−/−) mice whereas overexpression of Skp2 in mice led to tumor development in the prostate, suggesting that a SKP2 deregulation-induced oncogenesis may be tissue specific." (PMID 29594129, 2018). "Our results suggest that the anti-tumor efficacy of FKA is related to its ability to suppress Skp2." (PMID 30250282, 2018). "As we know, the regulatory elements of cell cycle such as cyclins, CDKs, CDKIs, Skp2 and FoxO are key components that respond to mitogenic and survival signals to control the cell cycle, which play an important role in controlling tumor proliferation and cell survival." (PMID 29360760, 2018). "In addition, using immunohistochemistry (IHC), we also observed that simvastatin treatment increased AMPK phosphorylation, reduced STAT3 phosphorylation and decreased Skp2 expression in tumor tissues." (PMID 28230855, 2017). "More importantly, Skp2 deletion in a Skp2 knockout mouse model has been shown by multiple groups to markedly restrict tumorigenesis under different conditions of tumor initiation and promotion, including PTEN, ARF, pRB inactivation, as well as HER-2/Neu overexpression." (PMID 28335434, 2017). "Note that tumour growth rate was the lowest in combinational group due to SKP2 depletion." (PMID 28090088, 2017). "Downregulation of Skp2 and Cks1 also resulted in cytokinesis failure, which may inhibit tumor growth." (PMID 28525372, 2017). "Recent studies also suggest that Skp2 inactivation induces tumor senescence via p21 and p27 and that this phenomenon may be partially under androgenic control in Pca." (PMID 29371946, 2017). "Skp2 could suppress tumor-suppressor effects of FoxO through promoting the degradation of FoxO in the nucleus via ubiquitination." (PMID 29018223, 2017). "Similarly, 46 (71.8%) of the 64 patients with high SKP2 expression of tumor and 28 (32.9%) of the 85 lower expression of tumor died of disease during the period of follow-up." (PMID 27317767, 2016). "Importantly, overexpression of Skp2 abrogated rottlerin-mediated tumor suppressive activity, whereas down-regulation of Skp2 enhanced rottlerin-triggered anti-tumor function." (PMID 27582552, 2016). "The results from this study may partially explain our findings here, in which SIRT2/Skp2/p27 controls NSCLC cell growth, in which SIRT2 appears to be a tumor suppressor and Skp2 appears to be an oncogene." (PMID 26942878, 2016). "The expression of tumor SKP2 could be categorized into lower expression (< 10.1 %) group and higher expression (≥ 10.1%) group." (PMID 27317767, 2016).